PCNA (proliferating cell nuclear antigen)
Diseases named in the same sentence as PCNA in open-access papers (continued):
Sharing a sentence is not in itself a finding about the gene and the disease.
IMAGe syndrome (4 papers, 2013 to 2024). IMAGe syndrome is characterized by the association of intrauterine growth retardation, metaphyseal dysplasia (and short limbs), adrenal hypoplasia congenita, and genital anomalies. "Mutations in the proliferating cell nuclear antigen (PCNA)-binding domain of the CDKN1C gene were recently identified in patients with IMAGe syndrome." (PMID 24098681, 2013). "We hypothesize that these differences in amino acid changes (arginine to leucine in SRS versus Arginine to Proline in IMAGe Syndrome) are associated with a both differential loss of binding to PCNA and the effects of modifier genes." (PMID 25861374, 2015). "Gain-of-function mutations affecting the highly conserved 279th amino acid within analogous proliferating cell nuclear antigen (PCNA) domains of the CDKN1C gene have been reported in IMAGe syndrome and familial SRS (p.Arg279Pro, p.Arg279Ser, p.Arg279Leu)." (PMID 38888172, 2024). "Loss-of-function mutations of p57Kip2 have been identified in BWS patients, and gain-of-function mutations in the Proliferating cell nuclear antigen (PCNA)-binding domain of p57Kip2 have been identified in growth retardation syndromes such as SRS and IMAGe syndrome." (PMID 27415617, 2016).
metastatic tumor (4 papers, 2017 to 2023). "And the PCNA staining revealed that RD@MBs + αPD-L1 also induced the maximal inhibition of metastatic tumor proliferation." (PMID 36759928, 2023). "RCC is a highly metastatic disease, and a higher expression of PCNA is thought to be an indicator of unfavorable prognosis." (PMID 28405545, 2017). "Furthermore, the numbers of hepatic lobes with metastatic tumors and the PCNA index were significantly decreased by Y15." (PMID 29221151, 2017). "Additionally, PCNA correlates directly with patient survival and metastatic tumor behavior." (PMID 28460440, 2017).
mild cognitive impairment (4 papers, 2020 to 2023). "On the other hand, neurons from the mild cognitive deficit, and AD patients do express cyclin B and proliferating cell nuclear antigen, which allows them to replicate their genome." (PMID 32155994, 2020). "Expression profile for cell cycle-related proteins proliferating cell nuclear antigen, cyclin D, and cyclin B in mild cognitive impairment to severe AD cases demonstrated the occurence of cell cycle events in both early and late stages of disease." (PMID 32765956, 2020).
non-Hodgkin lymphoma (4 papers, 1992 to 2022). Distinct from Hodgkin lymphoma both morphologically and biologically, non-Hodgkin lymphoma (NHL) is characterized by the absence of Reed-Sternberg cells, can occur at any age, and usually presents as a localized or generalized lymphadenopathy associated with fever and weight loss. "Proliferating Cell Nuclear Antigen (PCNA) is a protein known to play a key role in DNA replication and repair in non-Hodgkin's lymphoma." (PMID 36281462, 2022). "The prognostic value of immunoperoxidase staining for proliferating cell nuclear antigen (PCNA) was studied in a series of 140 non-Hodgkin's lymphomas with median follow-up of 9 years." (PMID 1358164, 1992).
Osteochondroma (4 papers, 2015 to 2019). A common, benign cartiliginous neoplasm arising from the metaphysis of bone. "The thicker cartilage cap, the larger bone formation rate and the higher PCNA positive rate indicated a higher proliferative activity of condylar osteochondroma." (PMID 31842965, 2019). "The thicker cartilage cap, higher bone formation rate and higher PCNA positive rate indicated a higher rate of proliferative activity in condylar osteochondroma." (PMID 31842965, 2019). "This study attempted to compare the histological features of mandibular condylar hyperplasia and condylar osteochondroma using hematoxylin-and-eosin (H&E) staining, and immunohistochemistry staining of PCNA and EXT1 with quantitative analysis method." (PMID 31842965, 2019). "The higher expression of osteogenic proteins in BPOP than in osteochondroma was coincident with increased expression of PCNA in the perichondral spinous cells and marrow osteogenic cells of BPOP." (PMID 26865041, 2016). "Moreover, the positive rate of PCNA staining in condylar osteochondroma was obviously higher than the rate found in condylar hyperplasia." (PMID 31842965, 2019). "Immunohistochemical staining showed that PCNA was mainly located in the undifferentiated mesenchymal layer and the hypertrophic cartilage layer, and there were more PCNA positive cells in the condylar osteochondroma (P = 0.007)." (PMID 31842965, 2019). "In addition, there were obviously more PCNA positive cells in condylar osteochondroma (p = 0.007)." (PMID 31842965, 2019). "Pathological diagnosis was osteochondroma; immunohistochemistry showed that the tumor exhibited a conspicuous expression of BMP-4 and BMP-2 but rarely expression of PCNA." (PMID 25664314, 2015). "Regarding the proliferative activity observed by PCNA immunoreaction, the BPOP specimen showed a conspicuous positive reaction in the spinous cells of the perichondral fibrous tissue and in some osteoblasts/fibroblasts of the osseous tissue, while osteochondroma was rarely positive." (PMID 26865041, 2016).
osteoporosis (4 papers, 2022 to 2024). A condition of reduced bone mass, with decreased cortical thickness and a decrease in the number and size of the trabeculae of cancellous bone (but normal chemical composition), resulting in increased fracture incidence. "In our previous research, we found that Enpp1 deficiency causes mouse osteoporosis via the MKK3/p38 MAPK/PCNA signaling pathway." (PMID 37370114, 2023). "The inhibition of MKK3/p38 MAPK/PCNA pathway plays an important role in the development of osteoporosis caused by Enpp1 deficiency, and LPA partially rescued the proliferation of pre-osteoblasts via the MKK3/p38 MAPK/PCNA pathway." (PMID 36243801, 2022).
radicular cyst (4 papers, 2013 to 2019). "The highest level of PCNA expression was seen in suprabasal layers of KCOT, followed by radicular cyst, CCOT and dentigerous cyst." (PMID 24551811, 2013). "The number of positive cells for PCNA in the epithelium of KCOT were significantly higher than dentigerous and radicular cysts." (PMID 24551811, 2013). "PCNA expression was higher in the suprabasal layer of KCOT, followed by radicular cyst." (PMID 24551811, 2013).
Stroke (4 papers, 2010 to 2025). Sudden impairment of blood flow to a part of the brain due to occlusion or rupture of an artery to the brain. "Stroke-associated conditions and oxidative endothelial injury can induce PCNA expression in vascular smooth muscle cells isolated from brain arterioles." (PMID 25215243, 2014). "The results showed that enhanced PCNA colocalized with CD31 was most apparent 21 days after stroke, and 12/15-LO gene knockout blocked these effects." (PMID 28436420, 2017). "Quantitative analysis shows that many NG2 positive cells were PCNA positive, indicating that even 42 days after stroke, OPCs actively proliferate." (PMID 20552017, 2010). "We performed behavioural tests to determine functional recovery after stroke; then, double immunofluorescence staining of CD31 and Ki67/PCNA was applied on brain tissue to evaluate the effects of 15-LO/15-HETE on angiogenesis in an MCAO mouse model." (PMID 28436420, 2017).
acute kidney injury (3 papers, 2015 to 2021). Sudden and sustained deterioration of the kidney function characterized by decreased glomerular filtration rate, increased serum creatinine or oliguria. "Attenuation of cisplatin-induced acute renal failure is associated with augmented PCNA expression." (PMID 26510880, 2015). "To investigate regenerative and proliferative parameters, we performed gene expression analyses on stathmin and proliferating-cell-nuclear-antigen (PCNA) gene expression, which are well-described markers in recovery from acute kidney injury." (PMID 32188161, 2020).
acute lymphoblastic leukemia (3 papers, 2003 to 2022). Leukemia with an acute onset, characterized by the presence of lymphoblasts in the bone marrow and the peripheral blood. "Then, the aim of this work was to characterize the structure and function of novel PCNA transcript variants to find a potential molecular maker of relapse in acute lymphoblastic leukemia." (PMID 36291073, 2022). "Finally, we quantified the PCNA transcript variants in acute lymphoblastic leukemia samples and identified their expression in this disease." (PMID 36291073, 2022). "Since the in vitro results were in agreement with the clinicopathological features and low expression of PCNA_V2 and PCNA_V4 was observed in relapsed patients, our results suggest that these transcript variants are potential molecular markers of relapse in acute lymphoblastic leukemia patients." (PMID 36291073, 2022).
Ataxia (3 papers, 2016 to 2024). Ataxia refers to impaired coordination of voluntary muscle movement. "Recently, the PCNA variant C148S has been associated with Ataxia-telangiectasia-like disorder type 2 (ATLD2)." (PMID 37511614, 2023).
ataxia telangiectasia (3 papers, 2016 to 2024). Ataxia-telangiectasia is the association of severe combined immunodeficiency (affecting mainly the humoral immune response) with progressive cerebellar ataxia. "A missense mutation in the proliferating cell nuclear antigen (PCNA), an essential DNA replication accessory protein, was identified in a single family with four patients sharing phenotypic similarities to XP, CS and also ataxia telangiectasia (AT)." (PMID 27004399, 2016).
bone tumor (3 papers, 2011 to 2020). "Furthermore, the anti-tumor effects of G721-0282 were observed in an xenograft in vivo model in association with the reduced expression of Chi3L1, PCNA, Cyclin D1, p-STAT3, as well as the increased expression of Chi3L1 was correlated with the p-STAT3 level in human bone tumor tissues." (PMID 31929760, 2020).
breast invasive ductal carcinoma (3 papers, 2013 to 2020). "PCNA is highly expressed in breast invasive ductal carcinoma, has been shown to be upregulated by the Notch signaling pathway, and to mediate increased proliferation of cells transfected with active Notch." (PMID 31107884, 2019). "In one case of ductal adenocarcinoma that had received neoadjuvant treatment, the levels of IGF1R/PCNA signals went from moderate to none with an apparent decrease in nuclear IGF1R as determined by IHC." (PMID 32701997, 2020).
chondrosarcoma (3 papers, 2012 to 2023). A malignant cartilaginous matrix-producing mesenchymal neoplasm arising from the bone and soft tissue. "Supplementary to the HDR and NHEJ pathways, described in the literature for other cancer entities, the MMR pathway with the key players EXO1, MSH3, and PCNA, is also clearly activated in chondrosarcoma cells after proton application." (PMID 34916568, 2021). "High-grade dedifferentiated components have been shown to have a higher malignant potential than low-grade chondrosarcoma components, with increased proliferation as demonstrated by expression of Ki-67 and proliferating cell nuclear antigen." (PMID 23227977, 2012). "In a previous work, we were able to show that, in addition to homologous-directed repair (HDR) and non-homologous end joining (NHEJ), the mismatch-mediated repair (MMR) pathway with the main players EXO1, MSH3, and PCNA were clearly activated in chondrosarcoma cells after proton application." (PMID 36768638, 2023).
colorectal adenocarcinoma (3 papers, 2015 to 2024). The most common type of colorectal carcinoma. "It had been reported that arginine can inhibit excessive proliferation of crypt cells in colorectal adenocarcinoma patients, and reduced PCNA expression in these cells." (PMID 38689278, 2024). "PCNA can be used as a biomarker of colorectal adenocarcinoma." (PMID 37049344, 2023).
colorectal tumor (3 papers, 2016 to 2022). "CORT also significant enhanced the expression of cell proliferation marker (Ki-67 and PCNA), NF-κB p65 and P-p65 as well as COX-2 in colorectal neoplasm of AOM/DSS-treated mice." (PMID 30665389, 2019).
cutaneous malignant melanoma (3 papers, 1999 to 2024). "The PCNA index is used as a successful predictor of local and distant recurrences in patients with primary cutaneous melanoma." (PMID 38727313, 2024).
diabetic nephropathy (3 papers, 2014 to 2022). "In addition, ECM proteins, such as α-SMA and PCNA, have been regarded as appropriate indicators of mesangial proliferative glomerulonephritis, including diabetic nephropathy." (PMID 25495844, 2014). "Mechanistically, circHIPK3 impeded miR-185 function and facilitated expression of cyclin D1, proliferating cell nuclear antigen (PCNA), TGF-β1, collagen I, and fibronectin, and compounded diabetic nephropathy." (PMID 36292157, 2022).
DNA repair disorder (3 papers, 2016 to 2023). "Consistent with roles in DNA repair processes, hypomorphic mutation of PCNA has been associated with clinical manifestations of human DNA repair disorders, including neurodegeneration, short status and photosensitivity." (PMID 27462463, 2016). "In general, patients with either PCNA-C148S or -S228I present with symptoms similar to other DNA repair disorders." (PMID 36990216, 2023). "With regard to the CNS environment, a homogenous missense mutation at p.Ser228Ile of the human PCNA locus has recently been identified to cause a neurodegenerative phenotype with clinical and molecular signatures of a DNA repair disorder, without affecting PCNA protein level and DNA replication." (PMID 28832631, 2017).
endometrial tumor (3 papers, 2003 to 2021). "In addition, expression of EGFR and HER-2/neu is associated with the aggressiveness of an uterine endometrial tumour, and expression of PCNA and Ki67 is correlated with clinical outcome." (PMID 12888828, 2003). "Correspondingly, immunohistochemical analysis revealed stronger expression of the cell proliferation marker PCNA in endometrial tumor sections." (PMID 33747724, 2021). "Taken together, these data demonstrate that the antitumor activity of MHY2256 towards endometrial tumor cell proliferation is related to reduce proliferating cell nuclear antigen expression in tumor tissues." (PMID 30217020, 2018).
gastric tumor (3 papers, 2015 to 2024). "So it is interesting to analysis the expression of PFTK1 in gastric tumor tissues and its coorelation with proliferating cell nuclear antigen (PCNA)." (PMID 26488471, 2015). "However, immunohistochemistry indicated similar PCNA+ proliferating cell numbers in the epithelium of gastric tumors of gp130F/F and gp130F/F:Nlrp3-/- 3mo and 6mo mice." (PMID 35299732, 2022).
glomerulonephritis (3 papers, 2012 to 2024). A renal disorder characterized by damage in the glomeruli. "In our future research, we plan to conduct PCNA and mTOR knockdown experiments to further validate their roles in the protective effects of 1.25(OH)2D3 against glomerulonephritis." (PMID 39636964, 2024).
head and neck squamous cell carcinoma (3 papers, 2021 to 2025). A squamous cell carcinoma that arises from any of the following anatomic sites: lip and oral cavity, nasal cavity, paranasal sinuses, pharynx, larynx, and salivary glands. "In the nucleus, it stimulates cell cycle progression by increasing the binding of EGFR to PCNA on squamous cell carcinoma of the head and neck (SCCHN) cancer cells." (PMID 38256018, 2024). "through genome-wide data and CMAP analysis identified MC-262 as a potential targeted therapy for head and neck squamous cell carcinoma (HNSCC), and its potential target in HNSCC is proliferating cell nuclear antigen." (PMID 34164339, 2021).
Hepatitis (3 papers, 2017 to 2022). Inflammation of the liver. "Our IHC results revealed the number of PCNA-positive hepatocytes in the Con-A group and confirmed the incidence of hepatitis in Con-A-challenged mice." (PMID 36615674, 2022). "Abundant expression of the DNA replication marker PCNA in DIDO3-deficient livers suggests that active cell proliferation, a sign of a regenerative response, is already underway at the peak of the mutation-driven hepatitis." (PMID 35672775, 2022). "In addition, Zhang and colleagues indicate that intravenous injection of IL-22 could enhance liver regeneration in mice with Con A-induced hepatitis after partial hepatectomy by augmentation of PCNA and cyclin D1 levels." (PMID 28578410, 2017).
Hypertension (3 papers, 2015 to 2022). The presence of chronic increased pressure in the systemic arterial system. "In addition, the levels of OPN and PCNA, WA%, WT%, and CA% correlated positively with BP, which indicated that hypertension caused by cell proliferation and remodeling in the thoracic aorta resulted from an increase in arterial stiffness and decrease in vascular elasticity." (PMID 27391973, 2016).
ischemia (3 papers, 2011 to 2022). A hypoperfusion of the BLOOD through an organ or tissue caused by a PATHOLOGIC CONSTRICTION or obstruction of its BLOOD VESSELS, or an absence of BLOOD CIRCULATION. "The very low proportion of PCNA+ and lack of TUNEL+ observed in primordial follicles suggested that they were in a quiescent status and can survive for a relatively long time period after suffering short-term ischemia." (PMID 26271079, 2015).
kidney cancer (3 papers, 2016 to 2023). Primary or metastatic malignant neoplasm involving the kidney. "This is consistent with our previous work, which reported that DACH1 level is inversely correlated with PCNA expression and that it inhibits cellular proliferation in kidney cancer." (PMID 27888806, 2016). "A study found that psoralen could slow the progression of kidney cancer by inhibiting the expression of MKI67, PCNA, MMP2 and MMP9 as well as the proliferation, invasion, and migration of kidney cancer cells HTB-47 and CRL-1932." (PMID 36627680, 2023).